SPDYA (speedy/RINGO cell cycle regulator family member A)
Description:
Regulates the G1/S phase transition of the cell cycle by binding and activating CDK1 and CDK2. Contributes to CDK2 activation without promoting CDK2 phosphorylation, by inducing a conformation change of the CDK2 T-loop that obstructs the substrate-binding cleft prior to kinase activation. Mediates cell survival during the DNA damage process through activation of CDK2.
Synonyms: Spy1; SPDY1; Ringo3; RINGOA
Tractability: No criterion of Open Targets' tractability assessment is met for any kind of drug.
Gene: Protein-coding gene on chromosome 2 (28,782,517 to 28,850,611, forward strand). Ensembl gene ENSG00000163806.
Subcellular location: Nucleus
Subcellular location (Human Protein Atlas): Nucleoplasm
Gene Ontology:
Molecular function: protein binding; protein kinase activator activity; protein kinase binding
Biological process: DNA damage response; G1/S transition of mitotic cell cycle; positive regulation of cell population proliferation; male meiotic nuclear division
Cellular component: nucleoplasm; nucleus; chromosome, telomeric region; nuclear envelope; XY body
Genetic constraint (gnomAD): Loss-of-function variants: 8 observed, 24.64 expected, observed/expected ratio (o/e) 0.32, 90% interval 0.19 to 0.59. The upper end of that interval is the gene's LOEUF score, 0.59, which puts it in group 2 of 6, group 1 being the genes least tolerant of losing a copy. Missense variants: 221 observed, 290.44 expected, observed/expected ratio (o/e) 0.76, 90% interval 0.68 to 0.85. Synonymous variants: 87 observed, 97.68 expected, observed/expected ratio (o/e) 0.89, 90% interval 0.75 to 1.06.
Homologues: Orthologues: macaque SPDYA (97% identical), pig SPDYA (89% identical), dog SPDYA (89% identical), chimpanzee SPDYA (84% identical), mouse Spdya (83% identical), rat Spdya (83% identical), guinea pig SPDYA (68% identical), tropical clawed frog spdya (62% identical), zebrafish spdya (49% identical). Paralogues in human: SPDYC (31% identical).
Diseases named in the same sentence as SPDYA in open-access papers:
SPDYA is named in the same sentence as 21 diseases in open-access papers, as found by Europe PMC text mining. Sharing a sentence is not in itself a finding about the gene and the disease. The quoted sentences say what the papers report.
Azoospermia (1 paper, 2025). Absence of any measurable level of sperm,whereby spermatozoa cannot be observed even after centrifugation of the semen pellet. "We generated a hypomorphic-SpdyA mouse model, the SpdyaA125V knock-in mice, which recapitulate a missense mutation originally identified in a patient with non-obstructive azoospermia (NOA)." (PMID 40826181, 2025).
cancers of the liver (1 paper, 2017). "This work focused on a cell cycle protein coined Spy1 (Speedy, RINGO) (gene SPDYA) that is elevated in a number of human cancers, including invasive carcinoma of the breast, as well as cancers of the liver, brain, and blood." (PMID 28423577, 2017).
Infertility (1 paper, 2019). "These genes play important roles in cell proliferation (RFX4, FOXM1, ASF1B), differentiation during spermatogenesis (CATSPERG, SPDYA, SPATA16, TSACC, TCP10L, DPY19L2) and motility of sperm cells during fertilization (DNAAF1); mutations in these genes may lead to infertility." (PMID 31671693, 2019).
mastitis (1 paper, 2025). Inflammation of breast tissue during lactation or postpartum due to an obstructed duct or infection. "Bta-miR-2285aj-5p appears to induce mastitis by activating the ERK1/2 and NF-κB pathways, leading to the positive regulation of SPDYA and FGL1." (PMID 39795030, 2025).
ovarian carcinoma (1 paper, 2025). A malignant neoplasm originating from the surface ovarian epithelium. "While SPDYA (also Spy1) typically shows overexpression in ovarian cancer, its hypermethylation in African tumours suggests overexpression may be a mechanism unique to non-African tumorigenesis." (PMID 41057544, 2025).
cancer (5 papers, 2014 to 2024). A tumor composed of atypical neoplastic, often pleomorphic cells that invade other tissues. "Speedy/RINGO cell cycle regulator family member A (SPY1) is a highly conserved “cyclin-like” protein, previously considered to be associated with several cancers." (PMID 36443440, 2023).
SPDYA also shares sentences with these, for which no sentence is quoted: tumours (11 papers); breast carcinoma (5); glioma (3); neuroblastoma (3); glioblastoma (2); infection (2); lung adenocarcinoma (2); amyotrophic lateral sclerosis (1); bacterial infection (1); colorectal cancer (1); invasive carcinoma of the breast (1); lobular carcinoma of the breast (1); lung carcinoma (1); ovarian tumours (1); pneumococcal infection (1).